LEF1 (lymphoid enhancer binding factor 1)
Diseases named in the same sentence as LEF1 in open-access papers (continued):
Sharing a sentence is not in itself a finding about the gene and the disease.
colon carcinoma (continued). "Interestingly, in colon cancer cell lines, we found that increasing intracellular miR-195-5p was able to reduce the protein expression levels of NLK, LEF1 and Cyclin D1 via JUP modulation." (PMID 38069408, 2023). "Examining a previously established collection of the normal colonic cells (HCEC) expressing the known oncogenic drivers of colon cancer such as truncated APC and mutant KRAS, we demonstrated that LEF1 was upregulated upon the expression of truncated APC and activated KRAS." (PMID 31623618, 2019). "Similar to LEF1, other WNT-related genes found in our RNA-seq to be regulated by MYC such as FOXQ1 and LRP6, were also transcriptionally repressed upon MYC knockdown in colon cancer cells." (PMID 31623618, 2019). "Here we report that MACC1 is a direct target of Wnt/β-catenin signaling pathway in colon cancer cells and that DBC1 functions as a coactivator for Wnt-mediated MACC1 expression by promoting the activity of a LEF1/β-catenin-dependent enhancer located in intron 1 of MACC1 gene." (PMID 30082743, 2018). "In this study, we generated colon cancer xenograft tumors and examined changes in cellular metabolism by immunohistochemical staining for phospho‐PDH (a marker of PDK activity), and markers of Wnt signaling (LEF‐1, β‐catenin)." (PMID 28183841, 2017). "Interestingly, our results indicated that inactivation of Wnt signaling via overexpression of the short form of LEF-1 also down-regulated the expression of CXCR4 in colon cancer cell lines, but CXCR4 expression was enhanced by the full form of LEF-1 in HT29." (PMID 22639890, 2012). "Our observations of an elevation in the expression of Lef1-FL in human endometrial tumors and of Lef1 expression in non-cancerous proliferative endometrium, but not in inactive endometrium are consistent with the findings from colon cancer." (PMID 22792274, 2012). "Therefore, it is essential to understand the molecular functions of these two LEF-1 isoforms and identify whether LEF-1 could be a new therapeutic target in colon cancer." (PMID 22639890, 2012). "FOXO1 inhibition impacted AXIN2, LEF1, and TCF7 in some, but not all, examined BBC and colon cancer cell lines." (PMID 37584250, 2023). "Importantly, most of WNT pathway genes induced by MYC, including DVL1, LEF1, RUVBL1, and RUVBL2, were also upregulated in tumor tissues when compared with the normal tissues from the same patients, suggesting that these genes may play a major role in colon cancer cells." (PMID 31623618, 2019). "We found that knockdown of LEF1 expression suppressed MMP2 and MMP-9 expression, but not MMP-7, indicating that the selective modulation of MMPs by LEF1 could have the biological significance in colon cancer progression." (PMID 24098538, 2013). "Moreover, knockdown of LEF1 expression could significantly decrease the levels of MMP-2 and MMP-9 protein, but not MMP-7 protein in shLEF1 cells compared to that of shNC colon cancer cells." (PMID 24098538, 2013).
prostate carcinoma (30 papers, 2009 to 2026). A carcinoma that arises from epithelial cells of the prostate gland. "LEF1 regulates the expression of the androgen receptor and is associated with the invasive ability of prostate cancer." (PMID 41516419, 2026). "In prostate cancer,LEF1 is involved in cell cycle regulation, proliferation, andmetastasis, and inbladder cancer, related to epithelial-to-mesenchymal transition (EMT) induction." (PMID 38100720, 2023). "The LEF1 O’PROTAC molecule LEF1 OP-V1 was found to be the most effective in degrading the POI in prostate cancer PC-1 and DU145 cells." (PMID 36986626, 2023). "LEF1 OP-V1 inhibited prostate cancer cell proliferation in vitro and tumor growth in vivo using PC-1 and DU145 xenografted mice." (PMID 36986626, 2023). "While, METTL3 has been found to be upregulated in prostate cancer, and METTL3 increases the cell proliferation and migration of prostate cancer cells by activating expression of LEF1 or Myc in an m6A methylation dependent manner." (PMID 33611339, 2021). "These FITC‐labeled LEF1 O'PROTACs were transfected into PC‐3 prostate cancer cells, which express endogenous LEF1." (PMID 34397171, 2021). "LEF1 is highly expressed in acute myelogenous leukemia, prostate cancer, small lymphocytic lymphoma, and other cancers." (PMID 34485109, 2021). "We demonstrate that LEF1 O'PROTAC promotes proteasomal degradation of LEF1 protein and inhibits LEF1 transcriptional activity and prostate cancer cell growth in vitro and in mice." (PMID 34397171, 2021). "We further verified the effectiveness of LEF1 OP‐V1 in DU145, another LEF1‐expressing prostate cancer cell line." (PMID 34397171, 2021). "Functionally, miR-34a is negatively correlated with the migration and invasion of prostate cancer cells through LEF1." (PMID 30781524, 2019). "METTL3 facilitated prostate cancer progression by upregulating LEF1 m6A methylation." (PMID 39867638, 2025). "Mechanistically, DNAPK interacts with LEF1 in prostate cancer." (PMID 35565454, 2022). "A cadherin switch (formed upon the suppression of E-cadherin and overexpression of N-cadherin) is involved in prostate cancer progression where E-cadherin obstruction by LEF1 and support of N-cadherin permit the cells to undergo epithelial-to-mesenchymal transition." (PMID 35201496, 2021). "Thus, LEF1 OP‐V1 can not only downregulate LEF1 protein, but also inhibit its transcriptional activity in prostate cancer cells." (PMID 34397171, 2021). "ETS-related gene (ERG) upregulates the downstream mediator transcription factor of the Wnt/β-catenin signaling pathway named Lymphoid enhancer-binding factor 1 (LEF1), which in turn enhances the androgen receptor expression and activity, leading to prostate cancer in an androgen-independent manner." (PMID 35201496, 2021). "Liang et al29 confirmed that miR‐34a targeted LEF1 to inhibit metastasis of prostate cancer cells." (PMID 34350720, 2021). "MiR-34a modulates the levels of LEF1 to regulate EMT in prostate cancer cells." (PMID 30781524, 2019). "Moreover, mutation of LEF1 was found to be associated with somatic sebaceous tumors, whereas mutation of CTCF is associated with invasive breast cancers, prostate cancers, and Wilms' tumors." (PMID 26895224, 2016). "Furthermore, LEF1 was identified as a potential marker for androgen-independent disease and as a key regulator of androgen receptor expression and prostate cancer growth and invasion." (PMID 21190562, 2010). "Likewise, miR-34a could be involved in the Wnt pathway by specifically repressing LEF1 to regulate the EMT process in prostate cancer." (PMID 30781524, 2019). "On the other hand, endocrine resistance and prostate cancer pathways are highlighted by genes such as MDM2 and LEF1, Oncogene-induced senescence, and MDM2 and ETS1." (PMID 40621499, 2025). "The degraders successfully promoted the degradation of two oncogenic TFs, lymphoid enhancer-binding factor 1 (LEF1) and ETS-related gene (ERG), and showed suppressive effects in prostate cancer modes." (PMID 37480049, 2023).
prostate carcinoma (continued). "Since LEF1 is a positive regulator of the Wnt signaling pathway, METTL3 can promote prostate cancer progression through the METTL3-LEF1-Wnt axis." (PMID 36008936, 2022). "Akin to LEF1 degrader, ERG O'PROTAC induces the degradation of ERG and inhibits prostate cancer cell growth." (PMID 34397171, 2021). "METTL3 also increases the m6A methylation of lymphoid enhancer-binding factor 1 (LEF1) mRNA, which promotes its protein expression and the progression of prostate cancer by activating the Wnt-β-catenin pathway (Ma, Cao & Zhao, 2020)." (PMID 32765970, 2020). "For example, lymphoid enhancer-binding factor 1 (LEF1) was found in ALL, selectin P ligand (SELPLG) was found in AML, and Bax was found in prostate cancer." (PMID 19915715, 2009). "oligonucleotide‐based proteolysis‐targeting chimeras (O'PROTACs), which employ unique DNA sequences as natural “ligand” of targeting proteins, are developed to effectively destruct lymphoid enhancer‐binding factor 1 (LEF1) and ETS‐related gene (ERG) and inhibit prostate cancer cell growth." (PMID 34397171, 2021). "We also investigated the androgen specific transcription factors such as Creb, and LEF1, which plays an essential role in the regulation of prostate cancer cells; however, these factors have not been observed in the DPCs of hair follicles in AGA." (PMID 29439547, 2018). "Moreover, the expression of LEF1/TCF transcription factors can beassociated with prognosis and treatment response in various cancer types, such ascolorectal and liver cancer, oralsquamous cell carcinomas,acute lymphoblastic leukemia, prostate cancer (Chen etal., 2018), and lung cancer." (PMID 38100720, 2023).
leukemia (29 papers, 2011 to 2025). A malignant (clonal) hematologic disorder, involving hematopoietic stem cells and characterized by the presence of primitive or atypical myeloid or lymphoid cells in the bone marrow and the blood. "This inactivation caused growth inhibition of the leukemia cells while also inhibiting the activation of the survival genes Bcl2 and survivin by c-Myc and LEF-1." (PMID 40805157, 2025). "Point mutations of LEF1 located in exons 2 (K86E) and 3 (P106L) of LEF1 result in increased promoter activity and expression for c-myc and cyclin D1, causing increased leukemia cell proliferation." (PMID 38003292, 2023). "To rigorously demonstrate that LEF1 was required for growth of these leukemias, we created E2a-/- mice that were homozygous for alleles of Lef1 with loxp sites flanking the DNA binding domain." (PMID 35371057, 2022). "LEF1 appears essential for the survival of E2a-/- leukemias since siRNA-mediated knockdown of Lef1 causes cell cycle arrest and the death of leukemias in vitro." (PMID 35371057, 2022). "Lef1 is highly expressed in some cancers, such as colon, ovarian cancer, and leukemia, where it has been reported to be associated with poor prognosis and to be essential for cancer invasion and metastasis." (PMID 32492961, 2020). "Aberrant Lef1 expression has been widely associated with poor prognosis in leukemia and several solid cancers such as colorectal, lung adenocarcinoma, and endometrial carcinoma." (PMID 32492961, 2020). "In one report high LEF1 expression and mutation was associated with high-risk of leukemia and LEF1 high expression or mutations were related with leukemogenesis of ALL." (PMID 27901484, 2017). "An example of this is seen with LEF1, an enhancer binding TF associated with several malignant diseases such as leukemia." (PMID 28605766, 2017). "Our finding indicated high LEF1 expression and LEF1 mutation are associated with high-risk leukemia and our results also indicated that the high expression and/or gain-of-function mutations account for the oncogenic effect of LEF1 in ALL." (PMID 25942645, 2015). "Taken together, our findings indicate high LEF1 expression and mutation are associated with high-risk leukemia and our results also revealed that LEF1 high expression and/or gain-of-function mutations are involved in leukemogenesis of ALL." (PMID 25942645, 2015). "In the case of disease, abnormal regulation of Wnt components, such as aberrant expression of LEF-1, have been implicated in solid cancers and leukaemias." (PMID 25392452, 2014). "However, DKO leukemias had a more a rapid onset than E2a-/- leukemias mirroring the early development of T-ALL with Lef1 inactivating mutations." (PMID 35371057, 2022). "We found the novel LEF1 mutations could promote the cell proliferation of leukemia cells by regulation of gene expression of LEF1 targets: c-MYC and Cyclin D1." (PMID 25942645, 2015). "Here we found LEF1 is highly expressed in 25.0% adult ALL patients and LEF1 high expression was associated with high-risk leukemia factors (high WBC, Philadelphia chromosome positive, complex karyotype), shorter event-free survival (EFS), and high relapse rates in patients with B-ALL." (PMID 25942645, 2015). "MYB and lymphoid enhancer-binding factor-1 (LEF-1) cooperated in the prevention of apoptosis in the leukemia cells, and GSK3β inhibition was able to circumvent this anti-apoptotic pathway." (PMID 38835346, 2024). "We demonstrate that E2a-/- leukemias that arose in mice sufficient for LEF1 became dependent on this transcription factor for their survival." (PMID 35371057, 2022). "The few T cell progenitors that develop from E2a-/- DN2 thymocytes highly express LEF1, an effector of the Wnt signaling pathway, and LEF1 is required for the survival of E2a-/- leukemias." (PMID 35514954, 2022). "Like Tcf7-/- leukemias, E2a-/- leukemias have high expression of Lef1 and LEF1 is required for the survival and proliferation of these leukemias." (PMID 35514954, 2022).
leukemia (continued). "In contrast, Syk and Rasgrp1 are increased in DKO compared to E2A-/- leukemias but decreased after deletion of Lef1 from E2a-/-Lef1F/F leukemias." (PMID 35371057, 2022). "We generated 2 lines from the leukemias arising in these mice and used a retrovirus producing Cre to delete the DNA binding domain of LEF1." (PMID 35371057, 2022). "When LEF1 is present during the transformation process, leukemias can become addicted to its presence." (PMID 35371057, 2022). "Its efficacy has been demonstrated in leukemia, colon, colorectal, and ovarian cancer, all of which are well known for high Lef1 expression." (PMID 32492961, 2020). "Lef-1 is part of the Wnt/β-catenin pathway involved in many of the PON2-associated cancers, including leukemias and thus was the most promising candidate from this approach." (PMID 27322774, 2016). "Our in vitro results demonstrate, for the first time, an enhancement of PON2 transcription and translation through Wnt/β-cat mediated Lef-1 activation in leukemia and OSCC cells." (PMID 27322774, 2016). "In order to explore the effect of LEF1 and its mutations on ALL, we stably expressed LEF1-WT and its mutants K86E and P106L in Nalm6 B-ALL and Molt4 T-ALL leukemia cells with puromycin selection and also cells with vector only as control." (PMID 25942645, 2015). "Aberrant expression of LEF1 has been reported to be involved in solid cancers and leukemia; and LEF1 is required for the growth of leukemia cells." (PMID 25942645, 2015). "In the first class, oncogenes (RUNX1, FLT3, LEF1) or tumor suppressors (RUNX1, CEBPA) implicated in leukemia were selected." (PMID 24786086, 2014). "Recently, LEF-1 expression was shown to be critical for the proliferation and survival of leukaemia cells, and knockdown of LEF-1 in myeloid leukaemia cell lines (K562 and HL-60) resulted in rapid cessation of growth followed by apoptosis." (PMID 25392452, 2014). "Moreover, binding sites for hematopoietic transcription factors, including CEBPA, SPI1 and LEF1, are uniquely inaccessible in these leukemias." (PMID 38972954, 2024). "The increased expression of p21 could contribute to the reduced expansion of LEF1-deleted leukemias." (PMID 35371057, 2022). "To determine whether deletion of Lef1 impacted the transformation potential of E2a-/- thymocytes, we allowed the mice to age and monitored them for signs of leukemia." (PMID 35371057, 2022). "Lymphoid enhancer-binding factor-1 (LEF-1) is a key transcription factor of wingless-type (Wnt) signaling in various tumors and it is associated with a number of malignant diseases such as leukemia." (PMID 25805670, 2015). "Thus far, there have been several reports about the LEF1 expression in leukemia and its impact on outcome of the patients." (PMID 25942645, 2015). "Thus, we could speculate that Syk and Rasgrp1 are positively regulated by LEF1 or TCF1, gaining a dependence on high levels of LEF1 in E2a-/-Lef1F/F leukemias and TCF1 in DKO leukemias." (PMID 35371057, 2022). "Indeed, we note that Cdkn1a is increased in both DKO leukemias and E2a-/-Lef1F/F leukemias after deletion of Lef1 compared to E2a-/- leukemias suggesting that Cdkn1a could be a TCF1 target that is repressed by LEF1." (PMID 35371057, 2022). "This might explain the different results about the prognostic value of LEF1 in leukemia." (PMID 32856045, 2020). "Considering the fact that the LEF1 level of bone marrow samples in blood tumors was influenced by the percentage of the malignant hematopoietic cells and the stage of the leukemia, it might result in relatively decreased LEF1 level in bone marrow samples of leukemia." (PMID 32856045, 2020). "ELN-PAX5 interaction results in the decreased expression of LEF1, MB1, and BLNK, while PML-PAX5 is critical in the early stages of leukemia." (PMID 37335685, 2023).
leukemia (continued). "Overall, hippuristanol demonstrated the most potent and consistent inhibition of the IRES-containing transcripts (LEF1, RUNX1) in two different leukaemia cell lines." (PMID 25392452, 2014). "Ectopic over-expression of some NOTCH targets (e.g. C-MYC, LEF-1 and IL-7RA) can partly or fully substitute for NOTCH signaling to drive leukemia growth despite blockade of Notch signaling." (PMID 21326611, 2011). "LSCs are responsible for sustaining the leukemia cell clone through their capacity for continuous self-renewal, where β-catenin aberrantly activates β-catenin-dependent genes such as survivin, c-Myc, Axin2 or Axin1, TCF1, and LEF1." (PMID 40805157, 2025). "Besides, some of the DMRs with the strongest increases were adjacent to genes such as CEBPA, LEF1, PLK2, MEIS1 or TLE4, which have a known involvement in either leukemia or hematopoiesis." (PMID 38972954, 2024). "Here, using flow cytometry, we found that LEF1 and TCF1 protein are detected in E2a-/- leukemias and that LEF1, but not TCF1, was reduced after treatment of cells with a γ-secretase inhibitor, which antagonizes Notch signaling." (PMID 35371057, 2022). "QPCR analysis of sorted GFP+ cells from MigR1 or MigR1-Cre transduced cells revealed decreased Lef1 mRNA after transduction of E2a-/-Lef1f/f but not E2a-/- leukemias with MigR1-Cre." (PMID 35371057, 2022). "Further, Tcf7-/- leukemias highly express ID2 and LEF1, particularly in a subset of T cell progenitors with a gene signature predictive of high leukemic potential, suggesting that that suppression of E protein activity may be a feature of transformation in this model." (PMID 35514954, 2022). "Indeed, while E2a-/- leukemias are dependent on LEF1, inactivation of Lef1 in E2a-/- mice prior to transformation did not prevent transformation; rather, it reduced leukemia latency and resulted in leukemias with a unique gene expression program compared to E2a-/- leukemias." (PMID 35514954, 2022). "Further immunostaining was negative for cyclin-D1 and SOX11 and positive for CD43 and LEF1, overall consistent with CLL/SLL-induced subcutaneous leukemia cutis." (PMID 40893576, 2025). "Tcf7 mRNA appeared to be increased in DKO leukemias but TCF1 protein, unlike LEF1 protein, was expressed similarly in E2a-/- and DKO lines when evaluated by flow cytometry." (PMID 35371057, 2022). "We showed here that unlike LEF1, TCF1 is not regulated by Notch signaling in E2a-/- leukemias and therefore we hypothesize that Notch1 regulates Lef1 directly and independent of TCF1." (PMID 35371057, 2022).